BRAF (B-Raf proto-oncogene, serine/threonine kinase)
Diseases named in the same sentence as BRAF in open-access papers (continued):
Sharing a sentence is not in itself a finding about the gene and the disease.
tumor (continued). "The immunosuppressive factors can be reduced by blocking BRAF signaling to further improve the tumor microenvironment and make it more prone to T cell infiltration." (PMID 35860239, 2022). "We previously showed that RAS, BRAF and EGFR mutant alleles, which appear in circulating tumor DNA (ctDNA) during EGFR blockade, decline upon therapy withdrawal." (PMID 35915157, 2022). "Evidence of acquired resistance to BRAF and MEK inhibitors induced by tumour‐associated CD20+ B‐cells came from an in vitro analysis, which suggested this was mediated by B‐cell production of growth factor IGF‐1." (PMID 35218154, 2022). "Tumor-infiltrating Foxp3+ Tregs and CCR4+ cells were increased in cases with BRAFV595E mutation in comparison to that in cases with wild-type BRAF." (PMID 35131860, 2022). "Mutated BRAF V600E in this MAPK pathway enables the cells to proliferate excessively, leading to neoplasm formation." (PMID 36428683, 2022). "Upregulation of PD-L1 by various oncogenic mutations such as EGFR, BRAF, and activation of PI3K and JAK-STAT3 in tumor cells are critical pathways modulating tumor immune responses in the TME." (PMID 36361831, 2022). "BRAF status, size of tumour, location, tumour budding and tumour infiltrating lymphocytes were factored as lesser importance." (PMID 35323316, 2022). "The tumor was refractory to both combined immunotherapy and targeted therapy with BRAF/MEK inhibitors; however, it responded to combined MEK and CDK4/6 inhibition." (PMID 35565444, 2022). "BRAF target occupancy was then recorded as a function of time and distance from the vascularized tumor edge into its avascular tumor core." (PMID 35486732, 2022). "The activation of several oncogenic signaling pathways, including mTOR, BRAF, and c-Myc has been shown to increase cancer cell glycolysis and lead to lactate accumulation within the tumor microenvironment(TME)." (PMID 36573240, 2022). "In the context of the search for predictive biomarkers, the most useful are proteins that modulate the response to targeted therapy, and their expression changes depending on the degree of sensitivity/resistance of tumor cells to BRAF/MEK inhibitors." (PMID 35565444, 2022). "No additional clinically relevant molecular aberrations were reported including NRAS mutations, BRAF mutations, HER2 overexpression, NTRK fusions, or MSI-high (MSI-H) tumor types." (PMID 36969746, 2022). "Of relevance, tumor microenvironment plays an important role in protecting cancer cells from the anti-tumor activity of BRAF and MEK inhibitors through paradoxic upregulation of signaling pathways and survival factors." (PMID 35440004, 2022). "This is not only the case for immune checkpoint inhibitors (ICIs), which directly derepress anti-tumor T cell immunity, but also for targeted BRAF and MEK inhibitors, the efficacy of which has been at least partly attributed to immune engagement." (PMID 35444175, 2022). "Our recent report revealed that increased collagen deposition and tumor stiffening is an early response to BRAF inhibition to create a drug‐protective niche." (PMID 34957688, 2022). "A decreased frequency of circulating tumour BRAF V600E DNA was reported with vemurafenib (87% versus 0%, p < 0.001), with a poor incidence of acquired RAS alterations at progression." (PMID 36819812, 2022). "In contrast, simultaneous blockade of EGFR and BRAF produced synergistic inhibition of tumor growth in murine CRC models through enhanced MAPK suppression." (PMID 36530921, 2022). "For example, BRAF inhibitors display an exquisite affinity towards mutant BRAF, thereby their highly specific, tumor-selective effects in cells harboring BRAF-V600E." (PMID 36358912, 2022).
tumor (continued). "BRAF class I inhibitors (BRAFi) selectively bind to the mutated V600E BRAF protein, thus inhibiting MAPK/ERK signaling and the related effects on tumor growth." (PMID 35875139, 2022). "By analysing 17128 tumour samples, BRAF fusions were identified in 42 cases (0.2%), the most frequent partner genes being AGK, DOCK4 and TRIM24." (PMID 36230797, 2022). "Hot/inflamed profiles were found in 52% of all cases, and high scores of Tumor Inflammation Signature were observed in 42% of the metastatic BRAF-CRCs." (PMID 36010943, 2022). "Patients with MSS, RAS and BRAF wild-type mCRC and a primary tumor located in the left colon are considered suitable candidates for first-line anti-EGFR treatment in combination with chemotherapy." (PMID 36230751, 2022). "We detected interactions between BRAF and its fusion partners exclusively in tumor samples containing BRAF fusions." (PMID 36503484, 2022). "However, how BRAF mutation affects the tumor immune microenvironment (TIME) is unknown." (PMID 36543792, 2022). "In this review, we will describe the interaction between GM, the immune system and BRAF/MEK-targeted therapy in the context of how they collectively impact anti-tumor efficacy." (PMID 36233289, 2022). "This is because activation of oncogenes (e.g., RAS in lung or BRAF in nevi) or loss of tumour suppressor (e.g., PTEN in the prostate) induces senescence, what restrains tumour progression." (PMID 36065138, 2022). "The immune profile of BRAF-MT CRC can be evaluated in future clinical trials or in the prospective cohort to enhance the understating of the tumor biology of BRAF-MT tumors and find a new treatment strategy for BRAF-MT CRC." (PMID 35625987, 2022). "Both the BRAF IdyllaTM Mutation test and the VE1 IHC are fast, sensitive, and specific methods, while requiring limited tumor material." (PMID 35328303, 2022). "The currently approved BRAF-MAPK pathway inhibitors are a mainstay of anticancer therapies for metastatic melanoma and other neoplastic diseases with activating and oncogenic MAPK pathway mutations." (PMID 35203304, 2022). "A recent study showed that proximal colon tumor localization exhibited a significant correlation with mutations in KRAS and BRAF." (PMID 35681771, 2022). "Pathological features that specialists were most unsure of included CDX2 status, EGFR status, Lymph node ratio, KRAS status, BRAF status and tumour budding." (PMID 35323316, 2022). "RAS oncogene mutations are found in about 50% of CRC tumours with KRAS being the dominant and NRAS less frequent, while BRAF mutations are reported in 5–10% of tumours, with up to 21% reported in cohorts of patients with unresectable metastatic CRC (mCRC)." (PMID 35610367, 2022). "In this study, the gene expression profiles of 89 immunotherapy-naïve BRAF-CRCs were generated using the PanCancer IO 360 gene expression panel to improve the knowledge of the mechanisms involved in tumor-suppressive immune functions in BRAF-mCRCs." (PMID 36010943, 2022). "We first systematically profiled BRAF expression, methylation, gene alterations, and its clinical and therapeutic implications across 32 TCGA cancer types covering 10,967 tumor samples." (PMID 35910024, 2022). "Significance correlations were found in MLH1 promoter methylation and gender, tumor position, tumor differentiation, MSI, MLH1 protein expression, and v-RAF murine sarcoma viral oncogene homolog B1(BRAF) mutation in CRC patients." (PMID 35721189, 2022). "For example, in tumour P12-NBL, RAS-MAPK activation in the primary tumour occurred through loss of NF1, whilst it occurred in the metastatic lesion due to BRAF-mutation." (PMID 36182817, 2022). "Currently, due to the reduced cost of genetic testing, the genotyping of tumor biomarkers such as BRAF, KRAS, NRAS, and MSI is possible." (PMID 36136880, 2022). "The immune signatures of the tumor microenvironment at each stage of BRAF/MEK targeted therapy were characterized." (PMID 36091815, 2022).
tumor (continued). "Although tumor biopsy is essential for investigating these markers, UC diagnosis is usually performed using cytological or molecular (BRAF assessment) tools in veterinary medicine." (PMID 36299636, 2022). "In this context, we revealed that BRAF mutations and MMR gene mutations were higher in the primary tumor tissues." (PMID 35592200, 2022). "BRAF T1799A mutation contribute to poor clinicopathologic outcomes of PTC, such as increased extrathyroidal invasion, lymph node metastasis, advanced tumour stage and tumour recurrence." (PMID 35748101, 2022). "The combination of Pexidartinib and BRAF inhibitors resulted in a significant inhibition of tumor growth by reducing the recruitment of M2 macrophage." (PMID 35874717, 2022). "Since previous studies of BRAF gene alterations in cancers are limited to a single cancer type and/or insufficient sample sizes, an integrative analysis across a variety of tumor types to investigate its function is of particular importance." (PMID 35910024, 2022). "Coexistence with the BRAF V600E mutation is associated with higher tumor aggressiveness in PTC than in TERT and BRAF mutations occurring alone." (PMID 35884820, 2022). "Nivolumab has proven to be effective in a range of melanoma tumor subtypes, including both treatment-naïve and pretreated tumors with either WT or mutant BRAF status." (PMID 35453572, 2022). "Although BRAF targeting is effective in tumor types carrying mutant BRAF, however, there is rapid resistance against BRAF inhibitors." (PMID 36071980, 2022). "Despite the remarkable anti-tumor efficacy demonstrated by BRAF inhibitors in the clinic, the development of drug resistance considerably limits long-term survival benefits." (PMID 35234863, 2022). "Currently, an IdyllaTM system for circulating tumor DNA in blood samples have already been developed for BRAF, KRAS, NRAS, and EGFR." (PMID 35474548, 2022). "MMP-14 is upregulated in BRAF inhibitor-resistant cell lines and human tumor samples, and its upregulation is dependent on TGF-beta." (PMID 35558554, 2022). "Preclinical models and translational data demonstrate that BRAF/MEKi have an immunomodulatory effect on the tumour microenvironment (TME), further strengthening the biological rationale of combining the complimentary clinical profiles of BRAF/MEKi and CPI." (PMID 35366166, 2022). "One patient had a BRAF WT tumor in the primary tissue and a BRAF MT (BRAFP277Hfs*2) tumor in the metastatic tissue." (PMID 35592200, 2022). "On IRT modelling, overall attitude towards TILs was “neutral”, ranking TILs similar to BRAF status and tumour budding in guiding adjuvant chemotherapy." (PMID 35323316, 2022). "Combination with MEK inhibitors neutralizes the paradoxical activation of the ERK pathway induced by BRAF inhibitors, modestly improving response rate and extending tumor control." (PMID 36500607, 2022). "A recent paper demonstrated that expansion and activation of CD103+ DC progenitors at the tumor site can enhance tumor responses to therapeutic PD-L1 and BRAF inhibition." (PMID 36361831, 2022). "BRAF and/or MEK inhibition has shown some efficacy in unique mutations, yet, long-term tumor control as seen in a third of V600E/K mutations is uncommon." (PMID 35380338, 2022). "While BRAF V600E tumors are initially responsive to BRAF inhibitors, prolonged treatment results in inhibitor resistance and tumor regrowth." (PMID 36358868, 2022). "Adjuvant BRAF plus MEK inhibition is more effective at delaying tumor recurrence in resected stage III CM than surgical management alone, and a clinical trial is underway to minimize side effects associated with this therapy." (PMID 35513054, 2022).
tumor (continued). "The treatment of the remaining vast majority of mCRC patients (who are microsatellite stable—MSS) is still based upon only a few molecular and/or clinical determinants: sidedness of the primary tumor location, RAS and BRAF mutational status." (PMID 36230751, 2022). "Combined therapy with BRAF/MEK inhibitors administered thereafter showed rapid results, with a dramatic reduction in tumor volume of 90% at 4 months, associated with symptom relief." (PMID 35757402, 2022). "The inhibition of these genes (dual EGFR/MEK and/or mTOR) resulted in a better response in tumor models exhibiting RAS family, BRAF or PIK3CA mutations." (PMID 36556139, 2022). "Our study provides a comprehensive view of BRAF expression, alteration, and clinical prognostic implications across 32 cancer types covering more than ten thousand tumor samples." (PMID 35910024, 2022). "The disease control rate was similar in patients with BRAF mutation and BRAFwt/KRASwt, but lower for patients with KRAS mutated tumours." (PMID 35574322, 2022). "The different patient characteristics suggested that the CRC was similar in male and female patients in terms of age group (age ≤ 40 years, vs. >40 years), location of the tumor, pathological staging, grade, KRAS mutation status and BRAF mutation status." (PMID 35565379, 2022). "Using targeted proteomics tools within a set of various cancer models we describe here the discovery and characterization of a composite phosphorylation signature associated with tumor addiction to four distinct oncogenes, MET, EGFR, ALK and BRAF." (PMID 36494469, 2022). "A multicenter phase II trial (the CHRONOS trial) of anti-EGFR rechallenge therapy with panitumumab guided by monitoring of the mutational status of RAS, BRAF, and EGFR in circulating tumor DNA (ctDNA)." (PMID 36147443, 2022). "Exact primary tumor location affects anti-EGFR antibody efficacy in a rather continuous than a dichotomous fashion in RAS/BRAF wild-type mCRC patients." (PMID 35158793, 2022). "Several studies have proven the favorable efficacy and safety of VEGFR inhibitors and inhibitors of other tumor-associated targets (including EGFR, FGFR, BRAF, c-Met, HDAC, tubulin, ERα and PIM1) combination therapy in patients with tumors." (PMID 35799213, 2022). "The detection of BRAF V600E SNV in cfDNA released by living, dying, or dead tumor cells using patient plasma or serum has also been associated with tumor burden, minimal residual disease, treatment response, and clonal evolution." (PMID 35205608, 2022). "Preclinical and translational evidence suggest BRAF/MEK inhibitors modulate the tumor microenvironment (TME), providing rationale for combination with immunotherapy." (PMID 36505793, 2022). "Analysis of the cell–cell interactions in each sample revealed inter-tumor heterogeneity in terms of interaction intensity and pattern in bilateral PTC even with the same BRAF V600E mutation." (PMID 35515000, 2022). "In contrast to glutamine-induced BRAF inhibitor resistance, other studies have proposed a model in which low levels of glutamine in tumor core regions induce resistance to BRAF inhibitors." (PMID 35011702, 2022). "In the current study, following a comprehensive and cross-tumor systematic research of BRAF alterations of known functional class, we showed that each class of BRAF alterations approximately constitutes 1/3 of total BRAF-mutant NSCLC." (PMID 35884534, 2022). "The upregulation of BRAF can lead to the high expression of PD-1 on the cancer cells, thereby promoting tumor angiogenesis and malignant proliferation." (PMID 35935973, 2022). "Many new BRAF fusions have been identified over the last couple of years, with one study identifying 29 different BRAF fusions across seven different tumor types." (PMID 35169893, 2022). "Third, analyzing only the BRAF and KRAS hotspot variants limits the benefits of this method to patients carrying one of these variants in tumor tissue." (PMID 35159118, 2022).
tumor (continued). "In a preclinical study, inhibition of the BRAF-Tak1-p38 MAPK-IKKα axis has been demonstrated to sensitize tumor cells to different chemotherapeutic agents." (PMID 35053591, 2022). "This indicates that pancreatic ITPN cannot be considered as a KRAS-independent entity, also taking into account that MAPK-pathway can be activated in this tumor type also through BRAF alterations (case #7)." (PMID 36056133, 2022). "Targeted therapy is designed to interfere with critical biological pathways (such as RTK/RAS/MAP-Kinase pathway and I3K/Akt signaling) and block dysregulated proteins (such as EGFR and BRAF) which play essential roles in tumor formation, growth, and invasion." (PMID 36059550, 2022). "The present study confirmed that upregulation of HTR3A was associated with shorter PFS in BRAF-mutated PTC, supporting a tumor-promoting role of HTR3A and a potential role in predicting prognosis." (PMID 35757399, 2022). "Our results indicated that the methylation of BRAF and downstream genes were correlated with tumor occurrence." (PMID 35910024, 2022). "In i3 tumor cells, published gene signatures related to MAPK activity and KRAS and BRAF activating mutations were more highly expressed." (PMID 35773407, 2022). "Resistance to BRAF‐targeted treatment frequently occurs because residual tumour cells acquire resistance to BRAF inhibitors by reactivating the MAPK pathway." (PMID 36282887, 2022). "Patients initially treated with BRAF ± MEK-inhibitors had a shorter TTNT upon tumor progression (1.0 vs. 3.0 months; p = 0.09)." (PMID 35565212, 2022). "For this reason, they added oncolytic virotherapy to BRAF inhibition in TC to obtain a more favorable tumor immune microenvironment, as well as increase the inflammatory status of cancers and ameliorate BRAF inhibitor therapy." (PMID 35628540, 2022). "The subtypes and tumour mucosa genera were associated with prognostic clinical covariates (tumour grade, localisation, TNM, BRAF mutation and MSI)." (PMID 34638284, 2021). "The BRS, which assesses the similarity of a sample’s expression pattern to that of a BRAF V600E or RAS mutant, is conventionally associated with mutational status, TDS score, and tumor histology." (PMID 34680332, 2021). "Restoring the expression of AIM2 in BRAF-mutant CRC cells greatly inhibits the tumor cell growth by inducing necrotic cell death." (PMID 33842454, 2021). "Another challenge after the successful initiation of BRAF/MEK inhibitors is to decide when to discontinue treatment, weighing the risk for tumor recurrence and treatment side effects against each other." (PMID 34828788, 2021). "This showed one facet of metabolic rewiring where the BRAF oncogene altered metabolite flux, in this case increasing acetoacetate, to drive tumor growth." (PMID 34831420, 2021). "Currently, the BRAF status is determined on archival tumor tissue or on fresh tumor tissue from an invasive biopsy." (PMID 33915880, 2021). "More than half (52.9%) and eight (5.1%) patients had tumours with RAS and BRAF mutations, respectively." (PMID 33782470, 2021). "Nevi are growth-arrested, clonal neoplasms of melanocytes, triggered by certain specific mutations in the MAPK pathway, usually BRAF V600E mutations." (PMID 34575678, 2021). "On the other hand, BRAF status, RFS event, and tumor location are considered as most significant risk factors of CRC in the training set." (PMID 33777735, 2021). "The observed concordance for the tumor-plasma NGS BRAF genotyping was also similar to the tissue-plasma concordance reported for the more sensitive method, ddPCR, and are in line with the results obtained for actionable mutations in other cancers." (PMID 34356096, 2021).